LYZ (lysozyme)
Description:
Lysozymes have primarily a bacteriolytic function; those in tissues and body fluids are associated with the monocyte-macrophage system and enhance the activity of immunoagents.
Synonyms: LZM; AMYLD5; LYZF1
Tractability: Small molecule: a structure with a bound ligand is known; it has a high-quality binding pocket. Antibody: its Gene Ontology location is reachable by antibodies, with high confidence; UniProt places it where antibodies can reach, with medium confidence; UniProt predicts a signal peptide or a membrane-spanning region. PROTAC: its protein half-life has been measured.
Gene: Protein-coding gene on chromosome 12 (69,348,381 to 69,354,234, forward strand). Ensembl gene ENSG00000090382.
Subcellular location: Secreted
Subcellular location (Human Protein Atlas): Actin filaments; Golgi apparatus; Nucleoplasm; Predicted to be secreted
Pathways (Reactome):
Immune System: Antimicrobial peptides; Neutrophil degranulation
Metabolism of proteins: Amyloid fiber formation
Gene Ontology:
Molecular function: identical protein binding; lysozyme activity
Biological process: defense response to bacterium; defense response to Gram-positive bacterium; killing of cells of another organism; antimicrobial humoral response; defense response to Gram-negative bacterium; inflammatory response
Cellular component: extracellular exosome; extracellular region; Golgi apparatus; azurophil granule lumen; specific granule lumen; tertiary granule lumen
Genetic constraint (gnomAD): Loss-of-function variants: 16 observed, 14.54 expected, observed/expected ratio (o/e) 1.1, 90% interval 0.74 to 1.65. The upper end of that interval is the gene's LOEUF score, 1.65, which puts it in group 6 of 6, group 1 being the genes least tolerant of losing a copy. Missense variants: 121 observed, 157.68 expected, observed/expected ratio (o/e) 0.77, 90% interval 0.66 to 0.89. Synonymous variants: 52 observed, 54.68 expected, observed/expected ratio (o/e) 0.95, 90% interval 0.76 to 1.2.
Homologues: Orthologues: chimpanzee LYZ (100% identical), macaque LYZ (89% identical), guinea pig LYZ (83% identical), rabbit LYZ (79% identical), pig LYZ (70% identical), rat RGD1306474 (64% identical), mouse Lyz3 (61% identical), dog LYZ (58% identical), tropical clawed frog lyz (57% identical), Drosophila melanogaster CG7798 (42% identical), Drosophila melanogaster CG30062 (39% identical), Drosophila melanogaster LysB (38% identical), and 8 more. Paralogues in human: LYZL1 (45% identical), LYZL2 (45% identical), SPACA3 (45% identical), SPACA5 (43% identical), SPACA5B (43% identical), LYZL6 (40% identical), LYZL4 (36% identical), LALBA (35% identical).
Diseases named in the same sentence as LYZ in open-access papers:
LYZ is named in the same sentence as 338 diseases in open-access papers, as found by Europe PMC text mining. Sharing a sentence is not in itself a finding about the gene and the disease. The quoted sentences say what the papers report.
amyloidosis (54 papers, 2005 to 2025). A disorder characterized by the localized or diffuse accumulation of amyloid protein in various anatomic sites. "This study investigates the impact of cysteine protease cathepsin B (CTSB) on amyloids associated with Alzheimer’s and Parkinson’s diseases, hemodialysis, and lysozyme amyloidosis." (PMID 39955315, 2025). "The first mutations leading to ALys amyloidosis were identified in exon 2 of the LYZ gene (p.Ile74Thr and p.Asp85His)." (PMID 37833900, 2023). "Amyloidosis caused by the deposition of lysozyme protein in the form of amyloid (ALys type amyloidosis) is an inherited autosomal dominant disease with incomplete penetrance." (PMID 37833900, 2023). "Taking into account the family history of the disease and the exclusion of other most common variants of amyloidosis, hereditary lysozyme amyloidosis was diagnosed." (PMID 37833900, 2023). "Mutations in the human lysozyme are associated with lysozyme amyloidosis, leading to the deposition of amyloid fibrils in various organs, such as the kidneys, gastrointestinal tract, lymph nodes, blood vessels, spleen, and liver." (PMID 37836734, 2023). "For the first time, we discovered a mutation in the first exon p.F21L of the lysozyme gene, which, together with p.T88N amino acid substitution, led to amyloidosis in members of the studied family." (PMID 37833900, 2023). "Here we report a lysozyme amyloidosis family with dominant kidney involvement, and carried a variant lysozyme p.Trp82Arg, which was identified by immunohistochemistry, mass spectrometry and DNA sequencing." (PMID 31395023, 2019). "Lysozyme amyloidosis is a hereditary disease in which mutations in the gene coding for lysozyme leads to misfolding and consequently accumulation of amyloid material." (PMID 27428539, 2016). "We have previously created a Drosophila model of lysozyme amyloidosis in which WT lysozyme and amyloidogenic variants were expressed both ubiquitously and solely in the eye." (PMID 27428539, 2016). "We have previously established a Drosophila melanogaster model for lysozyme amyloidosis to investigate in vivo behaviour of disease-associate lysozyme variants using the ubiquitous and retinal drivers Act5C-Gal4 and gmr-Gal4." (PMID 27428539, 2016). "Early kinetic studies on lysozyme mutants implicated in a systemic inherited amyloidosis have shown that the stability of the native state relative to folding intermediates is not as great in the mutant relative to the wild type." (PMID 24970204, 2013). "We have demonstrated here that in a normally functional organism, the ER quality control mechanisms suppress the secretion of destabilised lysozyme variants, including the I56T variant associated with amyloid disease." (PMID 21818368, 2011). "Human mutants of lysozyme are among the growing class of natively folded proteins implicated in organ-specific or systemic forms of amyloidoses." (PMID 21483680, 2011). "At first, these findings appear to be in contradiction to the fact that in patients suffering from lysozyme amyloidosis, the large quantities of fibrillar aggregates which accumulate appear to be comprised solely of the destabilised lysozyme variants." (PMID 21818368, 2011). "Notably, trypsin is known to be able to degrade lysozyme amyloids, which are associated with hereditary lysozyme amyloidosis." (PMID 39194629, 2024). "In addition, we will also test these compounds in different TTR amyloidogenic variants and other amyloid systems, such as the amyloid-beta peptide and lysozyme, which are implicated in Alzheimer’s disease and lysozyme amyloidosis, respectively." (PMID 35008816, 2021). "However, despite a huge accumulation of knowledge of the lysozyme molecules including disease-causing mutants, the molecular mechanism of the pathogenesis of lysozyme amyloidosis is not yet fully understood." (PMID 35111814, 2021). "Here we report a lysozyme amyloidosis family with variant lysozyme p.Trp82Arg in a Chinese family." (PMID 31395023, 2019).
amyloidosis (continued). "Massive deposits, as seen in lysozyme-associated amyloidosis or certain forms of TTR-associated amyloidosis, could be deleterious due to the volume–or to mechanical effects on heart movements, for example." (PMID 23390551, 2013). "This may suggest that in patients suffering from amyloidosis the destabilised nature of the variant lysozyme is of great importance to protein misfolding." (PMID 21818368, 2011). "Therefore, in the future, it is essential to investigate the molecular dynamics of the polymorphs in aqueous solutions in a wide range of time- and space-scales, and then integrate all the findings to profoundly understand the amyloid polymorphism and eventually pathogenesis of lysozyme amyloidosis." (PMID 35111814, 2021). "Thus, if the pathological event in lysozyme amyloidosis is due to toxicity caused by intermediate lysozyme aggregates, an increased presence of SAP could potentially rescue toxicity by reducing the pool of these toxic species." (PMID 31978114, 2020). "We have previously suggested that the onset of lysozyme amyloidosis may be linked to the inability of the UPR to target for degradation the entire population of amyloidogenic variants, allowing a proportion of these species to aggregate and accumulate in the body as amyloid deposits." (PMID 27428539, 2016). "Overall, this study demonstrates that all phenoliccompounds tested influence the fibrillogenesis of human lysozyme.This finding encourages further exploration of various phenolic compoundsin the search for potential drugs to treat amyloidosis-related diseases." (PMID 40852308, 2025). "Together, these NMR and MD data provide the first direct structural information on the intermediate state, offering insights into targeting lysozyme amyloidosis." (PMID 40557600, 2025). "The expanding utility of amyloid-based materials in nanomedicine underscores the translational promise of lysozyme aggregates for RNA-based immunotherapies and gene-silencing strategies." (PMID 41012432, 2025). "This study focused on evaluating the degradation potential of CTSB on amyloid fibrils with varying clustering tendencies, associated with Alzheimer’s and Parkinson’s diseases, hemodialysis, and lysozyme amyloidosis." (PMID 39955315, 2025). "Hereditary amyloidosis comprises more than 30 subtypes, including TTR, ApoA-I, ApoA-II, gelsolin, lysozyme amyloidosis, cystatin C amyloidosis (ACys), fibrinogen Aα-chain, β2-microglobulin, ApoC2-II, and ApoC39." (PMID 39152105, 2024). "As the conformation of lysozyme in the fibril is otherwise fundamentally different from native lysozyme, our data provide a structural rationale for the need of protein unfolding in the development of systemic ALys amyloidosis." (PMID 39511224, 2024). "These aggregates have been linked to several diseases, including Alzheimer’s, Parkinson’s, and lysozyme amyloidosis." (PMID 37836734, 2023). "Other manifestations of lysozyme amyloidosis include infiltration with amyloid deposits of the spleen (with subsequent splenomegaly), nerve ganglia, adrenal glands, thyroid gland, arterial vessels (including the temporal artery), and bone marrow." (PMID 37833900, 2023). "Along with a specific protein that determines the type of amyloidosis (lysozyme with the amino acid substitutions p.F21L/T88N), amyloid signature proteins were identified in the samples with a high degree of reliability (−10lgP ≥ 20)." (PMID 37833900, 2023). "Involvement of the heart is considered rare, but over the past five years, cases of lysozyme amyloidosis accompanied by damage to the cardiovascular system with hypertrophic cardiomyopathy and pericardial effusion have been described." (PMID 37833900, 2023). "Even more crucial is the detection of trace amounts of amyloid aggregates of lysozyme in biological fluids not only in connection with the early diagnosis of neurodegenerative diseases but also for lysozyme amyloidosis." (PMID 35214929, 2022).
amyloidosis (continued). "Understanding the dynamical features of polymorphs is thus crucial not only for deepening our understanding of amyloid polymorphism, but also for ultimately understanding the mechanism of cytotoxicity and pathogenesis of lysozyme amyloidosis." (PMID 35111814, 2021). "Of note, when α-value was updated with additional amyloid proteins, such as lysozyme, insulin and semenogelin, the identification of amyloidosis subtyping resulted in agreement with NAC findings." (PMID 33805439, 2021). "Accumulation of amyloid fibrils of these proteins leads to the development of hereditary lysozyme systemic amyloidosis (ALys amyloidosis,) and dialysis-related amyloidosis (DRA,), respectively." (PMID 34063223, 2021). "Understanding the possible differences in dynamical behavior between the polymorphs is thus crucial to deepen our knowledge of amyloid polymorphism and eventually elucidate the molecular mechanism of lysozyme amyloidosis." (PMID 35111814, 2021). "There was a patient with hereditary lysozyme amyloidosis in this study who was diagnosed and typed by genetic analysis, because IHC cannot type without antibody." (PMID 34885818, 2021). "Model lysozyme amyloid fibrils, the accumulation of which leads to the development of hereditary lysozyme systemic amyloidosis (ALys amyloidosis,), were selected as one of the objects of study." (PMID 34063223, 2021). "There were seven patients in this study including two minor glomerular disease patients as control group, four AL-λ patients and one rare lysozyme amyloidosis (Alys) patient." (PMID 34885818, 2021). "In the present study, a Drosophila melanogaster model of lysozyme amyloidosis was used to study the impact of co-expressing a disease-associated variant of lysozyme with SAP in vivo." (PMID 31978114, 2020). "Moreover, the structural similarity of these proteins with human insulin and human lysozyme, which are associated with the injection-localized amyloidosis, and hereditary non-neuropathic systemic amyloidosis, respectively, make them ideal model structures for amyloid-related studies." (PMID 33362209, 2020). "The accumulation of large quantities of amyloid aggregates is characteristic of lysozyme amyloidosis." (PMID 31978114, 2020). "In our Drosophila model of lysozyme amyloidosis, the toxic effect observed appears to arise from intermediate species of F57I formed on the pathway leading to the more amyloidogenic-like lysozyme aggregates observed in the presence of SAP." (PMID 31978114, 2020). "Lysozyme (ALys amyloidosis) and beta-2-microglobulin (DRA), as proteins with significantly different secondary and tertiary structures and stability, were chosen by us as target proteins." (PMID 33081200, 2020). "Manifestations of lysozyme amyloidosis are variable, including heartburn, gastric pain, gastrointestinal bleeding, hepatic rupture, renal failure, sicca syndrome and rupture of lymph nodes." (PMID 31395023, 2019). "This preliminary study used a combination of 3D structural and residue interaction network analyses to support roles for residues 21, 62, 104, 112–117, and 122 in lysozyme amyloidosis." (PMID 30029603, 2018). "Lysozyme amyloidosis is a rare disease characterized by the deposition of amyloid fibrils of the enzyme lysozyme." (PMID 30029603, 2018). "The importance of the partially unfolded state for lysozyme amyloidosis has been demonstrated in vitro with the use of antibodies that stabilize the protein." (PMID 30029603, 2018). "Data from various computational approaches used in this study support a role for lysozyme residues 21, 62, 104, 112–117, and 122 in lysozyme amyloidosis." (PMID 30029603, 2018). "In this study, the gene expression of lysozyme, a major player in the innate immune system, was found to be increased in a comparable pattern as the amyloid pathology developed in transgenic mouse models of AD." (PMID 27562772, 2016).
amyloidosis (continued). "The widespread systemic involvement of lysozyme amyloidosis currently provides limited options for treatment, although kidney and/or liver transplantation appear to be promising palliative treatments." (PMID 29043133, 2015). "Protein misfolding and amyloid formation are an underlying pathological hallmark in a number of prevalent diseases of protein aggregation ranging from Alzheimer’s and Parkinson’s diseases to systemic lysozyme amyloidosis." (PMID 26571264, 2015). "To our knowledge, we have also for the first time identified the amyloidogenic component of lysozyme amyloidosis via laser microdissection and mass spectrometry from a bone marrow biopsy." (PMID 29043133, 2015). "Lysozyme amyloidosis is an exceedingly rare hereditary autosomal dominant amyloidosis, which is characterized by the precipitation of lysozyme protein within the body, leading to multi-organ dysfunction." (PMID 29043133, 2015). "We report and describe symptoms and gastrointestinal tract involvement in a new family with hereditary lysozyme amyloidosis." (PMID 25217048, 2014). "Studies on wild-type and mutant lysozyme found in lysozyme amyloidosis showed that amyloid fiber formation was most prominent under conditions where there was a high population of partially folded states (as compared to folded or fully unfolded)." (PMID 24970204, 2013). "We discuss the secretion of proteins in relation to lysozyme amyloidosis, in particular, and optimised protein secretion, in general." (PMID 21818368, 2011). "The relevance of our findings to lysozyme amyloidosis is discussed and we also use the information in an application of biotechnological relevance by devising a strategy for engineering the secretion of a scFv from P. pastoris." (PMID 21818368, 2011). "Fibrils were thus isolated from patients with DRA, systemic lysozyme, or transthyretin amyloidosis and analyzed for binding to aptamer WL-2 in dot blot assays." (PMID 17878167, 2007). "The same approach was successfully applied to cystatins, especially for postulating the mechanisms of amyloidosis of human cystatin C as well as human lysozyme." (PMID 15904486, 2005). "The objective of this paper was to extend application of this new HSS approach to search for functional sites, such as active and substrate binding sites in lysozyme and amyloidosis of cystatin families, to verify the reliability of our new method." (PMID 15904486, 2005). "Toxic effects originating from an overload of aggregates have been seen in lysozyme amyloidosis." (PMID 40627621, 2025). "Moreover, AQ blocked the fibrillation of human lysozyme by inhibiting aggregation and promoting dissociation of aggregates in human lysozyme amyloidosis was typically observed." (PMID 41304756, 2025). "In 2017, a case of lysozyme amyloidosis affecting the lungs and bronchi was described." (PMID 37833900, 2023). "In our study, we described a clinical case of lysozyme amyloidosis in a Russian family." (PMID 37833900, 2023). "Moreover, if the content of lysozyme and apolipoprotein A1 in the amyloid composition is comparable, the quantitative criterion in diagnosing the type of amyloidosis will lose its reliability." (PMID 37833900, 2023). "This type of amyloidosis has a very broad spectrum of clinical manifestations, depending on the location and volume of pathological deposits of lysozyme, which may affect all organs and tissues, with the exception of the central nervous system." (PMID 37833900, 2023). "The role of lysozyme in the development of amyloidosis was first described in 1932." (PMID 37833900, 2023). "Therefore, as a first step to ultimately understand the molecular mechanism of cytotoxicity and of amyloidosis including lysozyme amyloidosis, it is important to investigate the properties of lysozyme polymorphs in detail." (PMID 35111814, 2021). "HEWL can serve as a model protein to investigate lysozyme amyloidosis." (PMID 32198463, 2020).